PTH (parathyroid hormone)
Diseases named in the same sentence as PTH in open-access papers (continued):
Sharing a sentence is not in itself a finding about the gene and the disease.
Hypocalcemia (continued). "However, our ROC curve analysis revealed that the predictive utility of PTH for postoperative hypocalcemia was "moderate" (AUC = 64.5%; 95% CI: 48.4-80.5)." (PMID 40091995, 2025). "While the specificity value falls short of the ideal, it surpasses the sensitivity, suggesting that PTH determination may be somewhat more effective in ruling out postoperative hypocalcemia." (PMID 40091995, 2025). "Because of the rarity and complexity of the interaction of magnesium with the PTH secretion and high interdisciplinary clinical relevance, this review aims to raise awareness to the phenomenon of paradoxical hypomagnesemia in cases with hypocalcemia." (PMID 40740723, 2025). "Though conventional therapy aims to alleviate hypocalcemia and its symptoms, it does not restore normal PTH physiology and is associated with long-term complications including nephrocalcinosis, nephrolithiasis, and renal dysfunction." (PMID 39376010, 2025). "This case spotlights a dysfunction in the PTH axis and the structured approach required in the assessment of a non-specific finding of hypocalcemia to help discern an underlying rare aetiology." (PMID 41181744, 2025). "The causes of hypocalcemia can be broadly divided into either parathyroid hormone (PTH)-mediated or non-PTH-mediated (e.g., vitamin D deficiency) disorders." (PMID 41181744, 2025). "The development of diastolic dysfunction in patients with chronic kidney disease may result from disorders of (Ca-P) metabolism, including hypocalcemia, decreased levels of calcitriol, and increased levels of serum phosphorus and parathyroid hormone (PTH)." (PMID 39906471, 2025). "Newer calcimimetic agents include etelcalcetide, which achieves a 10% greater reduction in PTH levels compared to cinacalcet but does not improve gastrointestinal tolerance and carries a higher risk of hypocalcemia." (PMID 40149691, 2025). "In dogs, as in humans, it can be hypothesized that, during AKI, hypocalcemia and hyperphosphatemia may contribute to the rising in PTH concentrations to restore mineral homeostasis, as indicated by the strong correlation between iCa and P with PTH." (PMID 40005891, 2025). "Pseudohypoparathyroidism emerges as the leading hypothesis based on treatment-resistant hypocalcaemia, elevated parathyroid hormone (PTH) levels, and extensive calcification." (PMID 41322841, 2025). "Biochemically, PTH resistance profiles may feature hypocalcemia, hyperphosphatemia, and high serum PTH levels." (PMID 41181744, 2025). "Elevated PTH levels observed in our cohort could reflect secondary hyperparathyroidism, a compensatory response to prolonged hypocalcemia, while higher ALP levels indicate ongoing osteoblastic activity and bone turnover." (PMID 41210018, 2025). "Based on the patient’s clinical presentation, brain imaging results of bilateral and symmetric intracranial calcifications, and laboratory results showing severe hypocalcemia, hyperphosphatemia, and a low PTH level, a diagnosis of Fahr’s syndrome secondary to hypoparathyroidism was made." (PMID 40070612, 2025). "Binary logistic regression analysis revealed that non-prophylactic intravenous calcium supplementation, high level of preoperative parathyroid hormone (PTH) and alkaline phosphatase (ALP), and low level of preoperative serum calcium were risk factors for severe hypocalcemia." (PMID 41367906, 2025). "Of the 159 patients who had undergone total thyroidectomy, eight (5%) had postoperative day 1 (POD1) parathyroid hormone (PTH) < 10 pg/ml, of whom three (2%) developed hypocalcaemia treated with calcium ± vitamin D, two with undetectable PTH at POD1 and one with PTH <5 pg/ml at POD1." (PMID 40066888, 2025). "In isolated cases, pathogenic mechanisms include activating autoantibodies against the calcium-sensing receptor (CaSR), which suppresses parathyroid hormone (PTH) secretion despite hypocalcemia, as shown in sporadic patients and in immune checkpoint inhibitor-induced hypoparathyroidism." (PMID 41465179, 2025).
Hypocalcemia (continued). "PTH is secreted in response to hypocalcemia and/or elevated serum phosphate." (PMID 41370665, 2025). "Recent studies examining the role of postoperative intact PTH levels and their changes in predicting hypocalcemia have assessed PTH levels at various intervals, ranging from intraoperative skin closure to 48 h after surgery, and even up to 4 days postoperatively." (PMID 40786097, 2025). "Three other independent families have recently been described with delayed ossification, characteristically observed in Eiken syndrome, that was associated with significantly elevated PTH levels, as evidence for PTH-resistance, and symptomatic, in some cases severe hypocalcemia." (PMID 40904804, 2025). "Hypoparathyroidism, along with hypocalcemia, may also contribute to hypomagnesemia, as PTH increases magnesium absorption in the kidneys and in the gut and its release from the bones." (PMID 40282004, 2025). "As AXT914 rectified the altered Ca2+e-mediated Ca2+i responses associated with the Nuf mouse CaSR mutation (Leu723Gln) in vitro, we proceeded to an in vivo assessment of this calcilytic in Casr+/Nuf mice, which have hypocalcemia and reduced plasma PTH concentrations." (PMID 40086735, 2025). "In conditions such as sepsis or endotoxemia, systemic elevations of cytokines (e.g., IL-1, IL-6) diminish PTH synthesis and impair active vitamin D production, collectively resulting in functional hypocalcemia that extends beyond mere insufficient dietary intake." (PMID 40284849, 2025). "Accordingly, our approach emphasizes contextual interpretation of PTH; correction of symptomatic hypocalcemia, hyperphosphatemia, and hypomagnesemia; and avoidance of iatrogenic extremes of calcium load and PTH suppression, alongside selective use of genetics for PFBC." (PMID 41531582, 2025). "Of these, the measurement of PTH is key to determining the etiology of hypocalcemia." (PMID 40717880, 2025). "Specifically, in human AKI, HPT is mainly driven by hypocalcemia, directly regulating PTH production by the parathyroid glands through a feedback mechanism, and secondarily promoted by hyperphosphatemia, which can chelate calcium, and by decreased calcitriol concentrations." (PMID 40005891, 2025). "Additionally, sepsis and multiple blood transfusions are known to contribute to hypocalcemia through various mechanisms, such as impaired PTH secretion, altered calcium homeostasis, and citrate toxicity." (PMID 40717880, 2025). "The PTH on POD1 is the more traditional predictor of postoperative hypocalcemia." (PMID 40786097, 2025). "Given the prolonged bone resorption phase and remarkably increased number of remodeling sites, bone formation will require a massive amount of calcium, resulting in severe hypocalcemia even though PTH concentration might still be in the normal range." (PMID 40026929, 2025). "In addition, hypocalcemia leads to the activation of the renin-angiotensin-aldosterone system directly or indirectly by increasing PTH production." (PMID 40290310, 2025). "Biochemically, PTH resistance is defined as hypocalcemia, hyperphosphatemia, and elevated serum PTH in the absence of vitamin D deficiency and with normal magnesium levels and normal renal function." (PMID 41170251, 2025). "Nevertheless, several published reports have highlighted that removal of larger parathyroid lesions may precipitate a marked decrease in PTH and total calcium levels, leading to clinical manifestations of hypocalcemia." (PMID 39941666, 2025). "At 35 years of age, due to markedly elevated PTH levels reaching 2100 pg/mL (normal range in general population 15–65 pg/mL) despite optimal medical treatment, he underwent total PTx, resulting in an initial reduction of PTH to 330 pg/mL and the onset of severe hypocalcemia." (PMID 40149691, 2025).
Hypocalcemia (continued). "In the case of severe or refractory hypocalcemia, we recommend the complementary measurement of serum albumin, ionized-bound calcium, and albumin-bound calcium, magnesium, PTH, and calcitonin and the assessment of vitamin D status, kidney function, and blood glucose status, including hemoglobin A1c." (PMID 40740723, 2025). "Co-administration of anti-resorptives with i.v. iron infusion is one such risk factor—the inhibition of bone resorption and reduced calcium efflux from bone compounds the iron-infused mediated increase in FGF23 and subsequent blunted parathyroid hormone response, thus resulting in hypocalcemia." (PMID 41445551, 2025). "However, in some patients with end-stage kidney disease, postoperative hypocalcemia can be severe and prolonged, despite normal or elevated levels of PTH." (PMID 39445258, 2024). "The area under the receiver operating characteristic (ROC) curves for day 1 PTH and drop in PTH for the prediction of day 1 hypocalcaemia (0.729 vs 0.726, respectively) and for 6-month hypoparathyroidism (0.964 vs 0.958, respectively) were similar, albeit slightly better for day 1 PTH." (PMID 38478048, 2024). "This case represents a scenario where PTH can be sampled directly from the source and this type of model could aid in the process of determining the etiology of hypocalcemia in COVID-19." (PMID 39355148, 2024). "The ensuing hypocalcemia stimulates the increased release of intact parathyroid hormone (PTHi)." (PMID 39124645, 2024). "High PTH in the presence of congenital hypocalcemia is not always due to receptor or post-receptor defect and can be due to a biologically inactive mutated PTH." (PMID 39435356, 2024). "Vitamin D deficiency might have also been present in the subgroup with normal/elevated PTH levels and hypocalcemia, which is why an analysis of the vitamin D status was recommended in these patients, too." (PMID 39636417, 2024). "The physiological response to this medically induced hypocalcemia will result in elevated PTH levels, which may be mistaken for primary hyperparathyroidism." (PMID 39189035, 2024). "Second, in clinical practice, the timing of hypocalcemia onset varies among patients, even when PTH levels are similarly reduced, and 1,25(OH)2D may also be involved." (PMID 38803480, 2024). "Thus, the earliest opportunity to predict hypocalcemia is to measure blood PTH levels as soon as possible after thyroid surgery." (PMID 40071247, 2024). "Hypoparathyroidism presents with hypocalcemia, raised serum phosphate, and low PTH levels." (PMID 39328612, 2024). "Lower PTH concentrations successfully identify patients at risk of developing transient hypocalcemia, whereas normal PTH finding excludes the possibility of developing persistent hypoparathyroidism." (PMID 38322433, 2024). "Studies revealed that measuring PTH levels 1 hour after surgery might be predictive of postoperative hypocalcemia." (PMID 38646308, 2024). "Hypocalcemia occurs due to decreased production of active vitamin D (1,25 dihydroxyvitamin D), which is responsible for gastrointestinal (GI) absorption of calcium and phosphorus and suppression of parathyroid hormone excretion." (PMID 39310569, 2024). "The most effective perioperative strategies for managing postoperative hypocalcemia and enabling early intervention and monitoring include closely monitoring postoperative PTH levels, administering perioperative calcium and vitamin D supplements, and tracking perioperative calcium level changes." (PMID 39258042, 2024). "Additionally, low levels of postoperative PTH four hours after surgery (3 - 10 pg/mL) have a sensitivity of 90% and specificity of 84% for predicting postoperative hypocalcemia." (PMID 40071247, 2024). "The lack of PTH is reported to induce the onset of symptoms associated with persistently low blood calcium levels (hypocalcemia) and elevated phosphates (hyperphosphatemia)." (PMID 37819413, 2024).
Hypocalcemia (continued). "Additionally, preoperative PTH and vitamin D levels, along with postoperative changes in calcium levels, were biochemical predictors of hypocalcemia after thyroidectomy." (PMID 40071247, 2024). "Moreover, placing mice on vitamin D-deficient diets under 0.25× RDI has been shown to lead to deficient levels of vitamin D after 4 to 6 weeks while avoiding hypocalcemia and elevated cut-offs for PTH levels." (PMID 39275253, 2024). "Therefore, PTH values, in conjunction with calcium values, patient symptoms and signs of hypocalcaemia, can be a valuable tool to manage patients in the postoperative period." (PMID 39649119, 2024). "Optimizing preoperative Ca, PTH, and 1,25(OH)2D levels may be crucial for reducing the incidence of hypocalcemia after thyroidectomy." (PMID 38803480, 2024). "This indicated an appropriate PTH response from the reimplanted gland, and that ongoing hypocalcemia may be due to insufficient PTH function to maintain systemic calcium levels or a peripheral interference with PTH level." (PMID 39355148, 2024). "The dysfunction of the parathyroid glands leads to hypocalcemia and hyperphosphatemia, with low parathyroid hormone levels in the presence of antibodies against parathyroid autoantigens, such as the calcium-sensing receptor, NACHT leucine-rich repeat protein 5, NALP5, or organ-specific antibodies." (PMID 38673639, 2024). "Consequentially,preoperative supplementation of calcium and vitamin D has been recommendedto prevent hypocalcemia after surgery, though its effectiveness wasfound to be less than certain.3−5 In addition, a surplus of vitaminD can suppress parathyroid hormone secretion further." (PMID 39022353, 2024). "Hypocalcemia with normal PTH may be attributed to increased calcium demand due to virus-dependent calcium influx or PTH resistance." (PMID 39262524, 2024). "Magnesium is essential for the maintenance of intracellular potassium concentrations, and hypomagnesemia is often associated with hypokalemia, due to urinary potassium wasting, and hypocalcemia, due to lower parathyroid hormone secretion and end organ resistance to its effect." (PMID 38592241, 2024). "The impaired PTH response to hypocalcemia in COVID-19 is yet to be understood." (PMID 39355148, 2024). "When magnesium levels are low, PTH secretion is impaired, leading to decreased mobilization of calcium from bone stores and reduced renal reabsorption of calcium, ultimately resulting in hypocalcemia." (PMID 39479146, 2024). "Intraoperative PTH measurements allow the early detection of hypocalcemia." (PMID 38646308, 2024). "In response to hypocalcemia, the parathyroid gland upregulates PTH levels." (PMID 39355148, 2024). "Hypocalcemia, hyperphosphatemia, and elevated parathyroid hormone levels may additionally occur as a result of renal failure." (PMID 39310569, 2024). "PTH measured on the first postoperative day had the highest sensitivity (80.2%), whereas calcium sampled one hour after surgery had the highest specificity (88.1%) in predicting symptomatic hypocalcemia." (PMID 38322433, 2024). "A PTH level < 15 pg/mL is usually a predictor of impending hypocalcemia." (PMID 40071247, 2024). "Testing confirmed a reinfection with SARS-CoV-2 and hypocalcemia, while PTH levels remained normal." (PMID 39262524, 2024). "It is possible that PTH levels were actually low but appeared normal due to the hypocalcemia." (PMID 39262524, 2024). "In PHP, resistance to PTH is defined by hypocalcemia, hyperphosphatemia and elevated PTH levels in the absence of vitamin D deficiency and renal insufficiency." (PMID 39267114, 2024). "Chronic hypocalcemia and the lack of action of PTH at the cardiac and vascular levels have been implicated as causal factors in cardiovascular complications." (PMID 38481445, 2024). "The authors speculated that the increasing PTH levels were due to parathyroid hyperplasia that gradually developed over time due to chronic stimulation of the parathyroid glands by hypocalcemia." (PMID 39435356, 2024).
Hypocalcemia (continued). "Postoperative hypocalcaemia may be better predicted and treated by using PTH as the primary decision-making tool, with calcium levels/clinical findings serving as an adjunct." (PMID 39649119, 2024). "Degradation of PTH decreases in hypocalcemia and, therefore, more PTH is available for secretion." (PMID 38672379, 2024). "Although retrospective studies suggest that postoperative intact Parathyroid Hormone (iPTH) may foresee hypocalcemia, optimal cut-off values and timing for iPTH evaluation vary." (PMID 38893037, 2024). "During the months following the initiation of treatment with calcitriol and calcium supplementation along with antitubercular therapy, the patient’s biochemical parameters gradually improved with resolution and hypocalcemia and normalization of serum phosphorus and PTH levels." (PMID 39351120, 2024). "PTH's primary role is restoring normal bone turnover by treating hypocalcemia." (PMID 39697967, 2024). "This mutation led to non-functional PTH causing hypocalcemia and triggering a secondary rise of biologically inactive PTH." (PMID 39435356, 2024). "This case represents a scenario where PTH can be sampled directly from the source and is a model that could aid in the process of determining the etiology of hypocalcemia in COVID-19." (PMID 39355148, 2024). "Disorders causing hypocalcemia can be divided into parathyroid hormone (PTH)-related and non-PTH-related disorders." (PMID 39246904, 2024). "Intact-Parathyroid hormone (iPTH) levels were in the lower limit of normal despite hypocalcemia." (PMID 37926713, 2024). "Hypoparathyroidism (HypoPT) is defined as a relatively uncommon endocrine disorder characterized by the presence of low levels of calcium in the bloodstream, a condition known as hypocalcaemia, alongside undetectable or inappropriately low levels of serum parathyroid hormone (PTH)." (PMID 38392648, 2024). "Patients with severe hypocalcemia and elevated PTH who present with new neurological symptoms despite normal general neurologic examination may warrant consideration for brain imaging to evaluate for Fahr syndrome." (PMID 38045865, 2023). "After successful parathyroidectomy of an adenoma, of 2.5 cm at its largest diameter, the PTH level decreased to a value of 10 pg/mL without associated symptomatic hypocalcemia." (PMID 37893182, 2023). "A frequent condition is hypocalcemia with PTH values in the normal range." (PMID 37198359, 2023). "Then, the reduction in PTH may lead to permanent hypocalcemia that is difficult to treat and severely compromises a patient's quality of life." (PMID 38027728, 2023). "Regarding hypocalcaemia, the reason is the decrease in PTH levels after MWA or RFA." (PMID 36892812, 2023). "Thus, in case of clinical suspicion (e.g., mild hypocalcemia or hyposphatemia), the index (Ca/P × PTH) can be used as valid index to identify a condition of PHP or HPT." (PMID 37854194, 2023). "Notably, the development of hypocalcemia due to PTH resistance in the renal proximal tubule typically occurs after infancy." (PMID 37920253, 2023). "However, larger drops lead to a paradoxical response inhibiting PTH secretion, leading to hypocalcemia refractory to Ca replacement, but responsive to Mg." (PMID 36651710, 2023). "Another study concluded that the preoperative PTH levels were associated with postoperative hypocalcemia, which has not been confirmed in the statistics of this study." (PMID 38116316, 2023). "Most authors, however, agreed that PTH levels taken within 1–6 h after skin closure may be predictive of postoperative hypocalcemia." (PMID 36902740, 2023). "Hypoparathyroidism, colloquially referred to as ‘underactive’ parathyroid gland(s), is characterized by an inadequate release of PTH necessary to maintain calcium equilibrium - this is demonstrated by hypocalcemia and either a low or inappropriately normal PTH measurement." (PMID 37790033, 2023).